NETO1 (neuropilin and tolloid like 1)
Description:
Involved in the development and/or maintenance of neuronal circuitry. Accessory subunit of the neuronal N-methyl-D-aspartate receptor (NMDAR) critical for maintaining the abundance of GRIN2A-containing NMDARs in the postsynaptic density. Regulates long-term NMDA receptor-dependent synaptic plasticity and cognition, at least in the context of spatial learning and memory (By similarity).
Synonyms: BTCL1; BCTL1
Tractability: Antibody: UniProt places it where antibodies can reach, with high confidence; UniProt predicts a signal peptide or a membrane-spanning region; its Gene Ontology location is reachable by antibodies, with medium confidence. PROTAC: its protein half-life has been measured.
Gene: Protein-coding gene on chromosome 18 (72,742,314 to 72,868,146, reverse strand). Ensembl gene ENSG00000166342.
Subcellular location: Cell membrane (Isoform 2); Postsynaptic density membrane; Cell membrane (Isoform 3); Secreted (Isoform 1)
Subcellular location (Human Protein Atlas): Golgi apparatus; Predicted to be secreted
Gene Ontology:
Molecular function: ionotropic glutamate receptor binding
Biological process: memory; neurotransmitter receptor localization to postsynaptic specialization membrane; regulation of long-term neuronal synaptic plasticity; regulation of neurotransmitter receptor localization to postsynaptic specialization membrane; visual learning; anterograde axonal transport of neurotransmitter receptor complex
Cellular component: excitatory synapse; postsynaptic density; postsynaptic density membrane; axon cytoplasm; extracellular region; glutamatergic synapse; plasma membrane; Schaffer collateral - CA1 synapse; synapse
Genetic constraint (gnomAD): Loss-of-function variants: 20 observed, 49.76 expected, observed/expected ratio (o/e) 0.4, 90% interval 0.28 to 0.58. The upper end of that interval is the gene's LOEUF score, 0.58, which puts it in group 2 of 6, group 1 being the genes least tolerant of losing a copy. Missense variants: 440 observed, 570.74 expected, observed/expected ratio (o/e) 0.77, 90% interval 0.71 to 0.83. Synonymous variants: 182 observed, 190.73 expected, observed/expected ratio (o/e) 0.95, 90% interval 0.85 to 1.08.
Homologues: Orthologues: chimpanzee NETO1 (99% identical), macaque NETO1 (99% identical), dog NETO1 (97% identical), pig NETO1 (97% identical), rabbit NETO1 (97% identical), mouse Neto1 (96% identical), rat Neto1 (95% identical), tropical clawed frog neto1 (88% identical), guinea pig NETO1 (82% identical), zebrafish neto1l (78% identical), zebrafish neto1 (64% identical). Paralogues in human: NETO2 (56% identical), DCBLD2 (20% identical), CUBN (16% identical), CNTNAP2 (16% identical), CNTNAP5 (16% identical), CNTNAP4 (16% identical), NRP2 (15% identical), CNTNAP3 (14% identical), CNTNAP3B (14% identical), NRP1 (14% identical), CNTNAP1 (14% identical), F5 (14% identical), and 23 more.
Diseases named in the same sentence as NETO1 in open-access papers:
NETO1 is named in the same sentence as 17 diseases in open-access papers, as found by Europe PMC text mining. Sharing a sentence is not in itself a finding about the gene and the disease. The quoted sentences say what the papers report.
epilepsy (3 papers, 2019 to 2025). A brain disorder characterized by episodes of abnormally increased neuronal discharge resulting in transient episodes of sensory or motor neurological dysfunction, or psychic dysfunction. "Since aberrant KAR-mediated excitability is implicated in certain forms of epilepsy, NETO1 represents a potential therapeutic target for treatment of both adult and early life seizures." (PMID 31044365, 2019). "Given that aberrant KAR-mediated transmission has been implicated in certain forms of epilepsy, NETO1 might provide an attractive target for development of novel treatments against adult and early life seizures." (PMID 31044365, 2019).
ovarian carcinoma (3 papers, 2020 to 2022). A malignant neoplasm originating from the surface ovarian epithelium. "However, the expression of NETO1 and the underlying mechanism in epithelial ovarian cancer (EOC) remain unknown." (PMID 32638511, 2020).
autism (2 papers, 2016 to 2021). Persistent deficits in social interaction and communication and interaction as well as a markedly restricted repertoire of activity and interest as well as repetitive patterns of behavior. "Forty-three percent of patients with 18q deletion were categorised to be at risk of autism and the likelihood was significantly increased when TCF4, NETO1 and FBXO15 were included in the region of hemizygosity." (PMID 27271878, 2016). "Furthermore, if the TCF4, NETO1, and FBXO15 genes were in the region of hemizygosity, the risk of autism increased significantly." (PMID 35056323, 2021).
schizophrenia (2 papers, 2011 to 2025). A major psychotic disorder characterized by abnormalities in the perception or expression of reality. "Using the replication sample set, we have conducted haplotype-wise analysis in order to investigate association between haplotypes within the NETO1 locus and schizophrenia." (PMID 22205981, 2011). "In this study, we investigated the association between eight SNPs within NETO1 and schizophrenia in the Japanese population." (PMID 22205981, 2011). "The goal of the present study was to evaluate the association between NETO1 and schizophrenia based on the JGWAS." (PMID 22205981, 2011). "We examined the association between schizophrenia and the neuropilin and tolloid-like 1 gene (NETO1)." (PMID 22205981, 2011). "First, we selected eight single nucleotide polymorphisms (SNPs) within the NETO1 locus, based on the Japanese schizophrenia genome wide association study (JGWAS) results and previously conducted association studies." (PMID 22205981, 2011). "NETO1 guides development of glutamatergic connectivity in the hippocampus by regulating axonal growth, and variations of the gene have been associated with schizophrenia." (PMID 40727427, 2025). "We investigated the association between the NETO1 gene and schizophrenia stratified by gender." (PMID 22205981, 2011). "We detected associations between NETO1 and schizophrenia in the meta-analysis, however, as the JGWAS dataset was included in the meta-analysis, evidence for association might be overestimated." (PMID 22205981, 2011). "However, to the best of our knowledge, no genetic association study specifically designed to evaluate the association between NETO1 and schizophrenia has been conducted." (PMID 22205981, 2011). "Moreover, several weak association signals (P<0.05) within the NETO1 locus were detected in the first GWAS of schizophrenia conducted in the Japanese population (JGWAS)." (PMID 22205981, 2011). "Therefore, the effect of onset age on the association between NETO1 and schizophrenia remains to be investigated in further studies." (PMID 22205981, 2011). "In addition, association between NETO1 and schizophrenia may be specific only for the patients with early onset age." (PMID 22205981, 2011). "We did not detect evidence for the association of NETO1 with schizophrenia in the Japanese population." (PMID 22205981, 2011). "In conclusion, we were not able to detect evidence for an association between NETO1 and schizophrenia in the Japanese population." (PMID 22205981, 2011). "Common variants within the NETO1 locus may not increase the genetic risk for schizophrenia in the Japanese population." (PMID 22205981, 2011). "Therefore, regulation of NR2 in hippocampus in schizophrenia may be relevant for the etiology of schizophrenia and NETO1 may play an important role in the molecular mechanism by maintaining the abundance of NR2A-containing NMDARs in the postsynaptic density of hippocampal neurons." (PMID 22205981, 2011).
atherosclerosis (1 paper, 2020). A disease characterized by the build-up of fatty material and calcium deposition in the arterial wall resulting in partial or complete occlusion of the arterial lumen. "Further studies are required to investigate the changes in promoter methylation in NETO1, FANK1, and SERHL2 in the development of atherosclerosis." (PMID 32398127, 2020).
leukemia (1 paper, 2016). A malignant (clonal) hematologic disorder, involving hematopoietic stem cells and characterized by the presence of primitive or atypical myeloid or lymphoid cells in the bone marrow and the blood. "Furthermore, we also identified a strong correlation in ETV6/RUNX1-positive leukemias between NETO1 and its adjacent, bidirectional lncRNA lnc-TIMM21-5 (r = 0.89) as well as between LRP8 and lnc-CPT2-7 (r = 0.70)." (PMID 27650541, 2016).
prostate adenocarcinoma (1 paper, 2021). "POSTN and NETO1 were correlated with androgen receptor expression, a main driver of prostate adenocarcinoma progression." (PMID 34133324, 2021).
psychosis (1 paper, 2019). "For the psychosis grouping, we observed a genome-wide significant burden of rare LoF and missense variants within GRIK5 (p = 7.83 × 10−10) and an increased burden of common and rare functional variants within NETO1 (p = 6.76 × 10−6)." (PMID 31844109, 2019).
tumor (4 papers, 2008 to 2022). "Moreover, NETO2, an important paralog of NETO1, has been investigated as a tumour‐promoting molecule in a variety of cancers and NETO2 expression has been found to have a significant correlation with poor prognostic results in these cancers." (PMID 32638511, 2020). "Taken together, these findings imply that NETO1 might contribute to carcinogenesis, tumour progression and poor clinical outcomes." (PMID 32638511, 2020). "Furthermore, NETO1 depletion inhibits the ability of KIF2A to promote tumour progression." (PMID 32638511, 2020). "Of course, future studies will be required to better explain these results and to clarify the mechanistic functions of ALPL, GPR68, NETO1, and VGF in the GBM TME and how they can mediate the success of CW application in the tumor resection cavity." (PMID 35884475, 2022). "On univariate survival analysis, NETO1 overexpression (HR 3.643; P < 0.001), older age (HR 2.293; P = 0.007), FIGO stage (HR 6.347; P < 0.001), tumour grade (HR 3.194; P = 0.008) and metastasis (HR 7.105; P < 0.001) were found to be associated with overall survival." (PMID 32638511, 2020).
cancer (3 papers, 2020 to 2022). A tumor composed of atypical neoplastic, often pleomorphic cells that invade other tissues. "The overexpression of NETO1 was associated with advanced cancer biology, indicated by metastasis, FIGO stage and serum CA125 level." (PMID 32638511, 2020). "Subsequently, experiments on a panel of EOC cell lines indicated that the silencing of NETO1 expression decreased the metastatic ability of cells which has a relation with advanced cancer biology." (PMID 32638511, 2020). "Abnormal expression of neuropilin and tolloid‐like 1 (NETO1) has been detected in some human carcinomas." (PMID 32638511, 2020). "NETO1 has been found to be abnormally expressed in human carcinomas." (PMID 34133324, 2021).
NETO1 also shares sentences with these, for which no sentence is quoted: cognitive deficits (2 papers); Alzheimer disease (1); behavioral disorders (1); cervical cancer (1); glioma (1); Intellectual disability (1); neurodevelopmental disorder (1).